LDHAL6A (lactate dehydrogenase A like 6A)
Description:
Catalyzes the interconversion of L-lactate and pyruvate with nicotinamide adenine dinucleotide NAD(+) as a coenzyme. Significantly increases the transcriptional activity of JUN, when overexpressed.
Synonyms: MGC23940; LDH6A
Tractability: PROTAC: UniProt records ubiquitination sites on it; ubiquitination databases record sites on it.
Gene: Protein-coding gene on chromosome 11 (18,455,824 to 18,479,601, forward strand). Ensembl gene ENSG00000166800.
Subcellular location: Cytoplasm
Pathways (Reactome):
Metabolism: Pyruvate metabolism
Gene Ontology:
Molecular function: L-lactate dehydrogenase (NAD+) activity; catalytic activity; oxidoreductase activity; oxidoreductase activity, acting on the CH-OH group of donors, NAD or NADP as acceptor
Biological process: lactate metabolic process; pyruvate catabolic process
Cellular component: cytoplasm; extracellular exosome; mitochondrion
Genetic constraint (gnomAD): Loss-of-function variants: 16 observed, 24.93 expected, observed/expected ratio (o/e) 0.64, 90% interval 0.43 to 0.98. The upper end of that interval is the gene's LOEUF score, 0.98, which puts it in group 4 of 6, group 1 being the genes least tolerant of losing a copy. Missense variants: 310 observed, 332.07 expected, observed/expected ratio (o/e) 0.93, 90% interval 0.85 to 1.03. Synonymous variants: 110 observed, 113.82 expected, observed/expected ratio (o/e) 0.97, 90% interval 0.83 to 1.13.
Homologues: Orthologues: chimpanzee LDHAL6A (100% identical), macaque LDHAL6A (98% identical). Paralogues in human: LDHAL6B (82% identical), LDHA (73% identical), LDHC (66% identical), LDHB (66% identical), MDH2 (25% identical).
Diseases named in the same sentence as LDHAL6A in open-access papers:
LDHAL6A is named in the same sentence as 8 diseases in open-access papers, as found by Europe PMC text mining. Sharing a sentence is not in itself a finding about the gene and the disease. The quoted sentences say what the papers report.
brain glioma (1 paper, 2021). A malignant glioma that involves the brain. "Due to this, we decided to analyze the expression levels of some glycolytic genes in pediatric glioma samples of different grades, and found that the HK1, PFKM, GAPDH, and LDHAL6A genes are overexpressed in human brain glioma biopsies." (PMID 34573317, 2021).
breast carcinoma (1 paper, 2025). "For luminal A breast cancer, we observed that genes associated with favourable prognosis—including key regulators of glucose metabolism HK3, LDHAL6A, apoptosis regulator PRKCB, and alcohol dehydrogenase ADH6—are not directly targeted by current treatments." (PMID 41007296, 2025).
glioma (1 paper, 2021). A benign or malignant brain and spinal cord tumor that arises from glial cells (astrocytes, oligodendrocytes, ependymal cells). "In the analyzed samples, we found an overexpression of the LDHAL6A gene in all samples, regardless of the CNS WHO grading, which is an agreement with the Warburg effect in glioma cells." (PMID 34573317, 2021).
ICF syndrome (1 paper, 2020). "Another study found a decrease in DNA methylation in LCLs of ICF syndrome patients near genes related to germline function (BOLL, SYCP2, LDHAL6A, and NCRNA00221) and an increase in mRNA levels, concordantly with a previous report of germline gene hypomethylation in ICF syndrome patients." (PMID 31963661, 2020).
type II diabetes (1 paper, 2024). "The LDHAL6A protein is a lactate dehydrogenase which is primarily expressed in the testes; however, it was also found to be differentially expressed in pancreatic β cells of patients with type II diabetes." (PMID 39217505, 2024).
tumor (4 papers, 2016 to 2025). "These ER+ tumours also demonstrate metabolic optimization through regulators such as HK3, LDHAL6A, ADH6, and PRKCB, which collectively shift metabolism toward greater efficiency." (PMID 41007296, 2025). "Pyruvate fermentation to lactate via LDH was more complicated with LDHA and LDHAL6B being increased in tumor tissues (2.55 and 0.69 log2 fold-change, respectively), while LDHB and LDHAL6A were decreased (-2.11 and -0.24 log2 fold-change, respectively)." (PMID 27128972, 2016).
cancer (1 paper, 2022). A tumor composed of atypical neoplastic, often pleomorphic cells that invade other tissues. "No significant upregulation of lactate dehydrogenases (LDHA-C and LDHAL6A) was found in cancer cell lines compared with normal cell lines, supporting the notion that activation of the TCA cycle is the preferred mode of energy production in the PCa cells rather than anaerobic glycolysis." (PMID 36282866, 2022).
LDHAL6A also shares sentences with these, for which no sentence is quoted: Obesity (1 paper).